ING1 (inhibitor of growth family member 1)
Description:
Implicated as a tumor suppressor gene.
Synonyms: p33ING1; p33ING1b; p24ING1c; p33; p47; p47ING1a
Tractability: PROTAC: UniProt records ubiquitination sites on it; ubiquitination databases record sites on it; its protein half-life has been measured.
Gene: Protein-coding gene on chromosome 13 (110,712,736 to 110,723,339, forward strand). Ensembl gene ENSG00000153487.
Subcellular location: Nucleus
Subcellular location (Human Protein Atlas): Nucleoplasm; Cytosol; Endoplasmic reticulum
Gene Ontology:
Molecular function: histone H3K4me3 reader activity; protein binding
Biological process: negative regulation of cell growth; negative regulation of cell migration; negative regulation of cell population proliferation; negative regulation of stem cell population maintenance; negative regulation of transcription by RNA polymerase II; negative regulation of transforming growth factor beta receptor signaling pathway; positive regulation of DNA-templated transcription; positive regulation of stem cell population maintenance; chromatin organization
Cellular component: nucleus; Sin3-type complex
Genetic constraint (gnomAD): Loss-of-function variants: 4 observed, 20.5 expected, observed/expected ratio (o/e) 0.2, 90% interval 0.095 to 0.45. The upper end of that interval is the gene's LOEUF score, 0.45, which puts it in group 1 of 6, group 1 being the genes least tolerant of losing a copy. Missense variants: 256 observed, 391.29 expected, observed/expected ratio (o/e) 0.65, 90% interval 0.59 to 0.73. Synonymous variants: 179 observed, 166.03 expected, observed/expected ratio (o/e) 1.08, 90% interval 0.95 to 1.22.
Homologues: Orthologues: macaque ING1 (99% identical), mouse Ing1 (89% identical), dog ING1 (89% identical), chimpanzee ING1 (87% identical), guinea pig ING1 (82% identical), tropical clawed frog ing1 (82% identical), rat Ing1 (78% identical), pig ING1 (76% identical), rabbit ING1 (73% identical), Drosophila melanogaster CG7379 (39% identical), zebrafish ing1 (27% identical), Caenorhabditis elegans lsy-13 (23% identical). Paralogues in human: ING2 (52% identical), ING5 (33% identical), ING3 (33% identical), ING4 (33% identical).
Diseases named in the same sentence as ING1 in open-access papers:
ING1 is named in the same sentence as 52 diseases in open-access papers, as found by Europe PMC text mining. Sharing a sentence is not in itself a finding about the gene and the disease. The quoted sentences say what the papers report.
breast carcinoma (17 papers, 2006 to 2025). "ING1 overexpression caused suppression of Hs578T human breast cancer cell lines, while its inhibition enhanced malignant phenotype of cells and so ING1 was introduced as a tumor suppressor gene." (PMID 36056353, 2022). "Low levels of ING1 are associated with increased motility, migration or invasion in colorectal, gastric and breast cancers." (PMID 34493070, 2021). "Decreased levels of ING1, loss of heterozygosity, or mutations in ING1 were detected in breast cancer, melanoma, head carcinoma, and astrocytoma." (PMID 34685579, 2021). "Ectopic overexpression of ING1 was found to cause cell cycle arrest, inhibition of metastasis and in vivo it reduced breast cancer cell-induced mortality in murine models." (PMID 31752342, 2019). "We used automated quantitative analysis (AQUA) to determine the levels of ING1 in the tumor associated stromal cells of 462 breast cancer samples." (PMID 26306560, 2015). "Future experiments to compare the gene expression profiles in response to ING1 expression in susceptible versus resistant breast cancer lines will help determine apoptotic pathways impinged upon by the ING1 protein." (PMID 22916295, 2012). "Our transcriptomics experiments, knocking down ING1 expression in MCF7 breast cancer cells, provide some mechanistic insight into how the loss of ING1 function might affect cell–cell junctions and promote invasion." (PMID 34493070, 2021). "Furthermore, multivariate analysis using Cox proportional hazards regression to adjust for important clinical covariates, confirmed that stromal ING1 expression was independently associated with DSS in breast cancer." (PMID 26306560, 2015). "For example, reduced ING1 expression was found in 73% of non-small cell lung cancer biopsies and 44% of breast cancer primaries, while no missense mutation were found in these lung cancer biopsies and only one missense mutation was found in 377 breast cancer carcinomas (0.27%)." (PMID 16755297, 2006). "Consistent with its tumor suppressive role, Ing1 protein levels are markedly lower in primary breast tumors and established breast cancer cell lines compared to normal tissues and cells." (PMID 40162308, 2025). "The authors demonstrated that p32 ING1 suppresses cell proliferation, and conversely its inhibition using antisense RNA showed opposite effect on cell growth of breast cancer cells." (PMID 36056353, 2022). "ING1 was the founding member of the family initially identified in breast cancer cells as a potential TSG and further studied compared to other genes in the past two decades." (PMID 36056353, 2022). "ING1 was isolated as a type-II tumor suppressor since its expression was downregulated in a panel of breast cancers." (PMID 31752342, 2019). "For example, the combination of ING1 with a chemical agent can act synergistically to block breast cancer cell growth." (PMID 28490335, 2017). "ING1 protein level was measured using quantitative fluorescence immunohistochemistry on the HistoRx AQUA® platform in breast cancer patient samples from the Calgary Tamoxifen cohort." (PMID 26306560, 2015). "Since fibroblasts constitute the majority of the stromal cells within a breast carcinoma, we used a human mammary fibroblast cell line to examine changes in cytokines and growth factors produced by these cells upon modulating levels of ING1." (PMID 26306560, 2015). "We have shown in this study that ING1 can specifically predict the survival of patients with luminal type breast cancer." (PMID 26306560, 2015). "Recently, we reported that reduced ING1 levels are correlated with increased metastasis in breast cancer patients." (PMID 26306560, 2015). "Here we analyzed levels of ING1 in breast cancer patients to determine its prognostic significance as a biomarker for breast cancer prognosis." (PMID 26306560, 2015).
breast carcinoma (continued). "ING1 expression also correlated with tumor grade in these patients and multivariate analysis showed that ING1 was an independent prognostic marker in the breast cancer cohort we tested." (PMID 26306560, 2015). "As our focus was on the expression of ING1 protein in the stromal region of breast cancer patients, we used the expression of ING1 in the vimentin positive region of normal breast tissue sample as our baseline control." (PMID 26306560, 2015). "Further testing needs to be done in this regard by validating the present observation in a different breast cancer cohort, along with clinical testing, to establish stromal ING1 as a bona fide biomarker in breast cancer." (PMID 26306560, 2015). "This phenomenon although anomalous to a typical tumor suppressor, defines a unique role of ING1 in breast cancer pathogenesis." (PMID 26306560, 2015). "Our study here provides substantial evidence for establishing ING1 as a probable biomarker for breast cancer." (PMID 26306560, 2015). "In this study we investigated the significance of ING1 expression in the stromal region of breast cancer patients and tested the prognostic/predictive value of stromal ING1 as a prognostic factor in the Calgary Tamoxifen Cohort." (PMID 26306560, 2015). "In this study we show that altering the levels of ING1 affects the expression of genes known to be altered in breast cancer, consistent with ING1 being initially identified as a gene repressed in breast cancer cell lines that can regulate gene expression." (PMID 24962136, 2014). "Prior studies showed that ING1 overexpression selectively killed breast cancer cells in vitro and in a mouse mammary model while reduced ING1 expression was seen in >40% of primary breast tumors." (PMID 24962136, 2014). "Transcriptome analysis showed that the pathway most affected by ING1 was breast cancer (p = 0.0008)." (PMID 24962136, 2014). "In this study, we evaluate the prognostic significance of ING1 in breast cancer with particular emphasis on distant metastasis-free survival." (PMID 24962136, 2014). "The first ING gene identified, human ING1, was discovered by PCR-mediated subtractive hybridization between normal mammary epithelial cells and breast cancer cells followed by a functional screen for tumorigenesis." (PMID 23585863, 2013). "Consistent with this, many studies have reported that levels of the ING1 tumor suppressor decrease in breast cancers." (PMID 23585863, 2013). "Our lab and others have found that Src levels generally increase in breast cancers, consistent with our current study in which Src reduces ING1 levels." (PMID 23585863, 2013). "ING proteins are down regulated in both familial and sporadic breast cancers and overexpression of ING1 can induce cell cycle arrest and apoptosis." (PMID 22916295, 2012). "This suggests the potential for using ING1 as a novel therapeutic agent since it enhances the efficacy of chemotherapeutic drugs when used in combination in breast cancer patients." (PMID 22916295, 2012). "ING1 expression is reduced in breast tumors and breast cancer cell lines but few studies have tested the effects of increasing ING1b in breast cancer cells." (PMID 22916295, 2012). "Notably, the apoptosis-inducing capacity of ING1 in breast cancer cell lines has been correlated with the amount of ING1 translocation to the mitochondria following exposure to UV." (PMID 35804879, 2022). "In PCa cells, ING1b silencing has also increased cellular senescence and induced expression of the effective cell cycle inhibitor p16INK4a.Conversely, upregulation of ING1 has been shown to inhibit cell growth and metastasis in breast cancer in vitro and in vivo." (PMID 36056353, 2022). "Overall, this study provides important pre-clinical data that could help establish ING1 as a prognostic and therapeutic agent for breast cancer." (PMID 26306560, 2015).
breast carcinoma (continued). "As high stromal ING1 expression significantly correlated with poor patient survival in the breast cancer cohort tested in this study, we next determined what cytokines might be regulated by ING1 in the stroma." (PMID 26306560, 2015). "In breast cancer patient samples, varying levels of ING1 expression were found in the stromal (vimentin positive) regions, which were quantified and then used for classifying patients with low stromal or high stromal ING1 expressing tumors." (PMID 26306560, 2015). "Specifically, higher ING1 expression in the stroma leads to poor survival of patients with luminal type breast cancer due to increase in MMP production, which may in turn allow cancer cells to escape and form secondary metastasis." (PMID 26306560, 2015). "Here we asked if ING1 expression could predict breast cancer patient outcome using an automated quantitative immune-histological technique to determine ING1 expression in the tumoral and stromal compartments of patient tissue samples." (PMID 26306560, 2015). "High levels of ING1 in stromal cells can promote the development of breast cancer through increased expression and release of MMPs and down regulation of TIMPs, which may be an underlying mechanism of reduced patient survival." (PMID 26306560, 2015). "Breast cancer patients were further dichotomized at the lowest tertile of ING1 expression (ING1< 226), as assessed in all patients for which there was an ING1 score (n=501), to identify low and high ING1 expressing tumors within the luminal and non-luminal subtypes." (PMID 24962136, 2014). "Given the link between low ING1 levels and lymph node involvement, we asked if ING1 could play a role in breast cancer cell invasion." (PMID 24962136, 2014). "INhibitor of Growth 1 (ING1) expression is repressed in breast carcinomas, but its role in breast cancer development and metastasis is unknown." (PMID 24962136, 2014). "ING1 was initially identified in a screen to identify genes repressed in breast cancer and it was subsequently seen to be downregulated in both familial and sporadic breast cancers." (PMID 24962136, 2014). "MDA-MB-468 breast cancer cell line that we have shown is sensitive to ING1-induced apoptosis." (PMID 23585863, 2013). "To determine whether ING1 expression was altered in breast cancer cells compared to normal breast epithelial cells we compared ING1 expression within our Tamoxifen-treated breast cancer cohort to a 95% confidence interval (C.I.)around the median results obtained from normal breast epithelium." (PMID 24962136, 2014). "Median tumor ING1 expression was 267 (red line) and fell at the lower end of the normal breast 95% C.I. (ING1=254-660, thin blue lines) indicating that ING1 expression tends to be lost in breast cancer cells as compared to the normal epithelium from which they are derived." (PMID 24962136, 2014). "Results show that stromal ING1 correlates with clinico-pathological characters like tumor grade (p = 0.001) and tumor size (p = 0.020) in the luminal (ER+/HER2-) breast cancer group consisting of 443 patients in the cohort." (PMID 26306560, 2015). "Our data show that ING1 protein levels are downregulated in breast cancer and for the first time, we show that altering their levels regulates metastasis in vitro and in vivo, which indicates that ING1 may have a therapeutic role for inhibiting metastasis of breast cancer." (PMID 24962136, 2014). "We identified two breast cancer cell lines, SKBR3 and MDA-MB468 that are unusually sensitive to ING1-induced cell death." (PMID 22916295, 2012). "ING1 (30th by MUFFINN yet 11,000th by the gene-centric methods in BRCA samples) was recently reported as a validated target of microRNA let-7b, which suppresses gastric cancer malignancy, and its down-regulation in breast cancer promotes metastasis." (PMID 27333808, 2016).
breast carcinoma (continued). "Five cancer cell lines including non-small cell lung carcinoma (H1299), osteosarcoma (U-2 OS and Saos-2), breast cancer (MDA-MB-468) and glioblastoma (U-87 MG) were used to evaluate the constructs and all lines were sensitive to the full-length and truncated forms of ING1." (PMID 27551477, 2015). "Results obtained were independently validated in vitro using cell based assays and an in vivo mouse experimental metastasis model, which establish that a strong negative correlation exists between metastasis in breast cancer patients and ING1 expression." (PMID 24962136, 2014). "AQUA analysis of samples from 532 breast cancer patients extends previous studies that have used limited numbers of samples and were lacking internal controls that reduction of ING1 levels frequently occurs in primary breast." (PMID 24962136, 2014). "Thus, mice with ING1 overexpressing breast cancer cells had no tumor burden in the knees, compared to controls which had a clear burden as determined by the BLI, μCT imaging and bone histology studies." (PMID 24962136, 2014). "Thus, we asked if ER negative breast cancer cell lines that are at a more advanced stage would be more sensitive to exogenous ING1 than ER positive cells." (PMID 22916295, 2012). "Here we also show that higher levels of ING1 correlate strongly with disease free survival (logrank p=0.013), disease specific overall survival (logrank p=0.0071), and distant metastasis free survival (logrank p=0.0003) in non-luminal, but not in luminal breast cancers." (PMID 24962136, 2014).
B-cell lymphomas (6 papers, 2010 to 2025). "When the chronically exposed ING1-deficient mice reached 15 months, they developed enlarged spleens and B-cell lymphoma localized to their lymph nodes, lungs, livers, and kidneys." (PMID 31752342, 2019). "While ING1-deficient mice had elevated incidences of B-cell lymphomas, histopathological analysis of two-year-old ING2 knockouts showed a higher incidence of soft tissue sarcomas that preferentially increased in males for currently unknown reasons." (PMID 31752342, 2019). "Interestingly, loss of ING2 resulted in an elevated incidence of soft-tissue sarcomas, while ING1-deficient mice preferentially developed B-cell lymphomas, supporting the role of ING proteins as tumor suppressors." (PMID 21767350, 2011). "This indicates that the p37ING1 isoform may play a role in the suppression of B-cell lymphoma in vivo, which is in line with the role of ING1 as a tumor suppressor." (PMID 21767350, 2011). "Furthermore, while Ing1−/− mice had elevated incidence of B-cell lymphomas, Ing2−/− mice had elevated incidence of histiocytic sarcoma." (PMID 21124965, 2010). "Similarly, Ing1 has been characterized as a tumor suppressor, with knockout mice exhibiting stunted growth, increased sensitivity to ionizing radiation, and the development of large clear B-cell lymphomas." (PMID 40162308, 2025). "In recent years, ING1 and ING2 have been described as tumor suppressor genes in various human cancer types, and both ING1 and ING2 knockout mice were found to spontaneously develop malignant diseases such as B cell lymphomas and soft tissue sarcomas." (PMID 31390718, 2019). "Interestingly, while none of the age-matched wild-type littermates developed B-cell lymphoma, a significant number of aged ING1 knock-out mice developed this type of tumor." (PMID 21767350, 2011).
gastric cancer (5 papers, 2014 to 2023). A primary or metastatic malignant neoplasm involving the stomach. "Downregulation of miR- 622 in gastric cancer promotes cellular invasion and tumor metastasis by targeting ING1." (PMID 25594007, 2014). "Studies have demonstrated that the expression of miR-622 is downregulated in gastric cancer, and the overexpression of miR-622 can inhibit cell invasion and tumor metastasis by targeting ING1 (inhibitor of growth family, member 1)." (PMID 31709182, 2019).
glioblastoma (5 papers, 2010 to 2019). The most malignant astrocytic tumor (WHO grade IV). "Taken together, these findings indicate that nitazoxanide as an autophagy inhibitor induces cell cycle arrest in glioblastoma via upregulated ING1 due to increased transcription and decreased post-translational degradation by late-stage autophagic inhibition." (PMID 30302016, 2018). "Our results showed that nitazoxanide suppressed cell growth and induced cell cycle arrest in glioblastoma by upregulating ING1 expression with a favorable toxicity profile." (PMID 30302016, 2018).